TNF (tumor necrosis factor)
Diseases named in the same sentence as TNF in open-access papers (continued):
Sharing a sentence is not in itself a finding about the gene and the disease.
inflammation (continued). "Preclinical and clinical studies show that the elevation of IgG against lipid peroxidation-derived antigens is associated with TNF-α elevation and the severity of liver inflammation." (PMID 28074118, 2016). "We concluded that Cu deficiency occurs following chronic TNF-α-induced lung inflammation and this likely plays an essential role in the inflammation-induced lung damage." (PMID 27378943, 2016). "Previous studies have shown that nerve inflammation and nerve injury caused rapid activation of spinal microglia and elevated expression of TNF-α, IL-1β, and IL-6, which promoted the nociceptive transmission in the spinal cord." (PMID 26064176, 2015). "ICAM-1 and TNF-α have been demonstrated to play a major role in the nerve inflammation associated with DPN." (PMID 26539228, 2015). "Allergic asthmatic inflammation is known to be caused by the secretion of a series of Th2 cytokines (IL-4, IL-5, and IL-13) and proinflammatory cytokines (TNF-α and IL-1β)." (PMID 24312355, 2013). "These authors have shown that TNF-α-deficient mice submitted to a model of airway inflammation and hyperresponsiveness presented lower numbers of γδ T lymphocytes in the lungs, whereas γδ T cell numbers were increased in the lungs of TNF-α transgenic mice." (PMID 23316161, 2012). "TNF-α is a primary mediator of the inflammatory response and closely linked to colonic inflammation of UC." (PMID 23365486, 2012). "TNF has been identified as a candidate gene for ozone-induced airway inflammation and hyperresponsiveness, and genetic variation in TNF and LTA has been associated with respiratory effects of ozone in humans." (PMID 17450233, 2007). "Tumor Necrosis Factor (TNF)-α is an inflammatory cytokine associated with liver inflammation." (PMID 40226809, 2025). "Studies have shown that the synovial inflammation of RA is associated with the release of inflammatory factors such as matrix metalloproteinases, tumor necrosis factor α and interleukin-6 after the activation of IL-17, TNF, TLRs, MAPKs, NF-κB and other pathways." (PMID 38491124, 2024). "TNF-α is implicated in all aging processes of skin, and chronic inflammation mediated by TNF-α is thought to contribute to the formation of wrinkles and other signs of aging, including loss of body mass, poor hydration, disintegration of dermis and epidermis junctions." (PMID 39063004, 2024). "Microglia activation results in chronic brain inflammation and an increase in proinflammatory cytokines such as TNF-α, IL-1β, and IL-6, which may be closely linked to the pathological features of HE." (PMID 39220284, 2024). "Cigarette smoking, causing airway inflammation, is considered to be associated with neutrophil, macrophage, and activated T lymphocyte infiltration and increased cytokine concentrations, such as IL-17A and TNF-α." (PMID 36139155, 2022). "In addition, IHC showed that the levels of IL-1β, MCP-1, and TNF-α (associated with intestinal inflammation) decreased by LA-1." (PMID 36325344, 2022). "Furthermore, the levels of major inflammatory cytokines (TNF-α, IL-6, and IL-1β) associated with hepatic inflammation were also significantly lower." (PMID 34204055, 2021). "The pro-inflammatory cytokines: namely TNF-α and IL-1β, and anti-inflammatory IL-10 are associated with lung inflammation and function, and studies using rodent models found an attenuation of both acute and chronic lung inflammation by polyphenol and anthocyanin intake." (PMID 34959825, 2021). "Elevation of TNFα and IL-6 is the hallmark of acute bowel inflammation." (PMID 34354689, 2021). "The oxidative stress status was associated with a state of cardiac inflammation and fibrosis that was evident by significant elevation of myocardial NF-κB p65, TNF-α and TGF-β1 contents reaching 833.33, 580.9, and 603.72%, respectively compared to the normal group." (PMID 33384599, 2020). "However, it is known that TNF-driven liver inflammation is associated with dysregulated expression of GPCR-associated proteins." (PMID 29445190, 2018).
inflammation (continued). "Similarly, in the model of transplantation induced lung inflammation the MPO deficient mice exhibited higher levels of TNF-α and the chemoattractant MCP-1 compared to the wild-type mice." (PMID 26998194, 2016). "Besides TNF-α, several other pro-inflammatory cytokines have been associated with intestinal inflammation." (PMID 25963636, 2015). "This study provides evidence that subacute (5 days) nose-only exposure to WPS caused early pulmonary inflammation evidenced by infiltration of neutrophils and lymphocytes, increased epithelial permeability, and concentrations of proinflammatory cytokines such as TNFα and IL-6 in lung tissue." (PMID 25780090, 2015). "However TNF-alfa levels are poor diagnostic markers for the severity of TNF-dependent liver inflammation." (PMID 17105669, 2006). "To test whether Irg1 is involved in osteoclastogenesis induced during joint inflammation, we used hTNFtg mice in which overexpression of human TNF causes a chronic inflammatory arthritis leading to osteoclast formation at the site of joint inflammation, and intercrossed them with Irg1−/− mice." (PMID 38986577, 2024). "Interestingly, the alveolar macrophage and monocyte populations had a predominant pro-inflammatory phenotype in mAlum offspring, evidenced by their increase in TNFα production and a parallel decrease in IL-10, a phenotype implicated in orchestrating and exacerbating pulmonary inflammation." (PMID 37646035, 2023). "This extract, orally administered at 25, 50, or 100 mg/kg at 96, 72, 48, 24, and 2 h before intestinal inflammation induction, showed anti-inflammatory effects associated with increased IL-10 synthesis, reduced oxidative stress, and reduction in the pro-inflammatory cytokines IL-1β, IL-6, and TNF-α." (PMID 37242733, 2023). "In addition, excessive intake of cholesterol may cause vascular inflammation, and pro-inflammatory cytokines such as TNF-α and IL-6 may stimulate the expression of adhesion molecules and chemokines such as VCAM-1, ICAM-1, and fibronectin in aorta tissue." (PMID 24364887, 2013). "TNF-α is a pro-inflammatory cytokine that plays a pivotal role in chronic inflammation and impaired cutaneous wound healing." (PMID 41598272, 2026). "As a contributor to chronic inflammation, a pro-inflammatory diet can elevate the levels of several cytokines, such as IL-1 and TNF-α, which are involved in the chemotaxis and migration of inflammatory cells into the bloodstream." (PMID 40211815, 2025). "By means of pathological staining and ELISA of periapical tissues, this paper revealed the mitigating effect of Pue on periapical inflammation, bone destruction and its suppression on the production of TNF-α, IL-1β and IL-6 in PD mice." (PMID 40312745, 2025). "The third metabolite tested, 1‐MNA, also has been suggested to be anti‐inflammatory, exerting a hepatoprotective effect in liver inflammation by suppressing IL‐4 and TNF‐α immune cell signaling." (PMID 39989432, 2025). "In a separate study, Glutamine decreased the levels of the inflammatory cytokines IL-1β, IL-6 and TNF-α in mice with ulcerative nodular inflammation." (PMID 39367233, 2025). "Mycobiome components like β-glucans can activate immune cells and promote pro-inflammatory cytokines (TNF-α, IL-6), exacerbating liver inflammation and bone resorption." (PMID 40235664, 2025). "Stenotrophomonas maltophilia is known to stimulate peripheral blood monocytes and alveolar macrophages to produce tumor necrosis factor-α, which plays a role in the pathogenesis of airway inflammation." (PMID 40464915, 2025). "Our study found a significant positive correlation between TMAO and TNF-α, a key cytokine involved in periodontal and systemic inflammation." (PMID 40131489, 2025). "Studies found that altered flora in patients with neonatal necrotizing small bowel colitis led to significant intestinal inflammation, resulting in increased expression of IL‐1, IL‐2, IL‐4, IL‐6, IL‐8, IL‐10, TNF‐α, IFN‐γ, and IL‐17 in samples." (PMID 40119640, 2025).
inflammation (continued). "During H. pylori infection, gastric epithelial cell-derived IL-33 promotes TNF-α production leading to gastric inflammation and bacterial colonization." (PMID 39857676, 2025). "Proinflammatory cytokines such as IL-1β and TNF-α play a central role in the initiation and maintenance of cerebral inflammation." (PMID 40141795, 2025). "The pathogenesis of RA involves the infiltration of leukocytes into synovial tissue and an increase in the production of inflammatory cytokines, such as interleukin (IL)-6 and tumor necrosis factor (TNF), resulting in chronic synovial inflammation." (PMID 40565171, 2025). "It is well known that macrophages are the main cells involved in synovial inflammation, and macrophages are activated to release inflammatory cytokines, especially TNF‐α, which triggers synovial inflammation and leads to the progression of OA." (PMID 39801258, 2025). "Further, visceral fat as an active secretory tissue can produce pro-inflammatory cytokines, including IL-1β, IL-6, and TNF-α, adipokines, and other biochemical modulators, which can contribute to systemic and peripheral vascular inflammation." (PMID 41010392, 2025). "In the present study, TiO2 NPs up-regulated mRNA expression of TNF-α and IL-1β in both liver and kidney suggesting its ability to induce hepatic and renal inflammation." (PMID 40447623, 2025). "Recent studies have indicated that GO can significantly diminish the production of the proinflammatory cytokines TNF-α, IL-1β, and IL-6 in LPS-induced macrophages or murine models, thereby reducing airway inflammation." (PMID 41562115, 2025). "This activation promotes the release of pro-inflammatory cytokines such as IL-6 and TNF-α, ultimately resulting in synovial inflammation and cartilage destruction." (PMID 40444099, 2025). "Systemic inflammation, characterized by elevated levels of cytokines such as interleukin-6 (IL-6), tumor necrosis factor-alpha (TNF-α), and C-reactive protein (CRP), plays a pivotal role in bridging these conditions." (PMID 40218134, 2025). "Chronic inflammation, accompanied by a marked elevation of inflammatory factors such as TNF-α, IL-6, and MCP-1, disrupts the spermatogenic niche and thereby impairs sperm maturation and viability." (PMID 41198620, 2025). "Tongxinluo also reduces vascular endothelial inflammation by inhibiting inflammatory factors such as TNF-α, IL-1β, and IL-6." (PMID 40761406, 2025). "Neutrophils are plentiful in the synovial fluid of patients with ICI-inflammatory arthritis and are involved in joint inflammation by releasing TNF-α, proteases, and reactive oxygen species (ROS)." (PMID 41239350, 2025). "Further, chronic intestinal inflammation and the release of proinflammatory cytokines (eg, tumor necrosis factor α, interleukine-6), can impair muscle function by activating protein-degrading pathways, such as the nuclear factor κB and JAK/STAT pathways." (PMID 41060265, 2025). "Modern pharmacological research indicates that XBCD can downregulate inflammatory mediators, notably IL-6 and TNF-α, thereby mitigating lung inflammation." (PMID 40342990, 2025). "HA exhibits anti‐inflammatory properties by inhibiting pro‐inflammatory cytokines, such as interleukin‐1 beta (IL‐1β) and tumour necrosis factor‐alpha (TNF‐α), and modulating the activity of immune cells involved in joint inflammation." (PMID 39210692, 2025). "Respiratory epithelial cells contribute to LPS-induced pulmonary inflammation in vivo by releasing cytokines such as tumor necrosis factor alpha (TNF-α) and interleukin-1." (PMID 40380298, 2025). "The secretion of IL-6, IL-1β, TNF-α and other inflammatory factors is usually significantly up-regulated in animal models of intestinal inflammation." (PMID 40746956, 2025). "HH also caused cardiac inflammation and fibrosis, especially in the OVX + HH group, which had elevated proinflammatory cytokines (IL-1β, IL-6, TNF-α) and decreased anti-inflammatory cytokines (TGF-β, IL-10)." (PMID 40108505, 2025).
inflammation (continued). "Activated macrophages infiltrate RA patients’ synovial fluid and secrete pro-inflammatory cytokines (TNF-α, IL-1β, and IL-6), which in turn promote synovial inflammation and lead to cartilage and bone destruction, which correlates with the severity of RA." (PMID 38966637, 2024). "Studies using the BEAS-2B cell model have shown that kaempferol reduces the expression of nicotinamide adenine dinucleotide phosphate oxidase 4 (NOX4) and suppresses TNF-α-induced airway inflammation." (PMID 39596066, 2024). "In our previous study on HMEC-1 cells, CNDs at concentrations ranging from 0.1–0.3 mg/mL were found to reduce TNF-α-induced endothelial inflammation." (PMID 38397822, 2024). "Previous studies have found that stem cells can produce immunomodulatory cytokines such as IL-10 to inhibit proinflammatory cytokine secretions such as TNF-α and IL-1β, thereby alleviating pulmonary inflammation." (PMID 39011319, 2024). "Previous studies have indicated that airway inflammation can lead to the release of pro-inflammatory cytokines such as IL-1β, IL-6 and TNF-α by the human broncho-epithelial cells and macrophages." (PMID 37851060, 2024). "Chronic systemic inflammation, through the activation of immune cells such as macrophages and T cells, leads to the production of inflammatory cytokines (TNF-α, IL-1, and IL-6) that directly influence bone metabolism." (PMID 38841589, 2024). "LPS induced lung inflammation, as evidenced by increased IL-1β, IL-6 and TNF-α levels in the serum compared to those in the Sham group." (PMID 38802896, 2024). "After the induction of nasal mucosal inflammation, the changes in IgE, IL-17, TNF-α, and IL-6 concentrations in the model group indicated upregulation of these markers and suggested successful induction of inflammation." (PMID 38369554, 2024). "Further, it is evident that the m6A reader, IMP2 can direct autoimmune inflammation through an IL‐17‐ and tumor necrosis factor‐α (TNF‐α)‐dependent C/EBP transcription factor axis." (PMID 39092763, 2024). "Celiac-disease-related intestinal inflammation is marked by accumulation of TNF-α producing ILCs in the gut mucosa, and depletion of ILCs preventing the poly I:C-driven intestinal damage." (PMID 39767818, 2024). "A study has proposed that pulmonary inflammation causes HAPE, and hypoxic stimulation causes the increase of tumor necrosis factor (TNF-α), interleukins (IL-1, IL-2, IL-6) and C-reactive protein (CRP) in blood." (PMID 37165489, 2024). "In conclusion, CND can inhibit TNF-α-induced endothelial inflammation, possibly due to its direct scavenging of H2O2 and the indirect upregulation of antioxidant enzyme NQO1 activity in endothelial cells." (PMID 38397822, 2024). "On note, renal inflammation in ADPKD has been associated with the expression and accumulation of proinflammatory cytokines, including TNFα, IL-6, IL-8 and MCP1." (PMID 38732256, 2024). "Our results suggested that inhibition of TNF‐α is a promising therapeutic approach for reducing brain endothelial inflammation and thus microvascular reperfusion injury after acute IS." (PMID 37789643, 2024). "To further understand the role of inflammatory cytokines in AHL‐related cochlear inflammation, we used real‐time PCR to assess the expression of three key cytokines, IL‐6, IL‐1β, and TNF‐α, in the cochlea." (PMID 39148148, 2024). "Intestinal inflammation is critically influenced by the overproduction of various inflammatory cytokines, with TNF-α playing a particularly pivotal role." (PMID 39410232, 2024). "As demonstrated in vivo, treatment of BALB/cN mice with 5, 10, and 20 mg/kg OLE suppressed signs of cisplatin-induced renal inflammation, including tissue modulation of TNF-α levels." (PMID 38540115, 2024). "This challenge produced a marked, neutrophil-driven lung inflammation (characterized by increased neutrophil numbers and TNF-α levels in BALF) in wild-type animals." (PMID 39137914, 2024).